BRCA2 (BRCA2 DNA repair associated)
Diseases named in the same sentence as BRCA2 in open-access papers (continued):
Sharing a sentence is not in itself a finding about the gene and the disease.
ovarian carcinoma (continued). "An assortment of mutations in the BRCA1 and BRCA2 genes have been shown to substantially increase the risk of breast and ovarian cancers." (PMID 32109416, 2020). "The introduction of PARPi in clinical practice for the treatment of patients with advanced ovarian cancer imposed changes in the molecular diagnosis of BRCA1/BRCA2 variants." (PMID 32850417, 2020). "Germline mutations in the tumor suppressor BRCA1 and BRCA2 genes have been strongly associated with an increased risk of breast and ovarian cancer." (PMID 33015058, 2020). "Women who carry a pathogenic mutation in BRCA1 or BRCA2 are at increased risk of developing breast and ovarian cancer." (PMID 32772980, 2020). "The frequency of BRCA1 and BRCA2 germline variants in women with ovarian cancer varies in the literature (6–41%), with the lowest prevalence observed in unselected series of patients with OC." (PMID 32850417, 2020). "The protein truncating mutations rs397508986 in BRCA1 and rs80358998 in BRCA2, found in the liver and pancreas samples, are components of genetic screening protocols for breast and ovarian cancer." (PMID 33198737, 2020). "Women with a BRCA1 or BRCA2 mutation have high lifetime risks of developing breast and ovarian cancer." (PMID 33014209, 2020). "BRCA1 and BRCA2 are the two well‐known tumor suppressors, and their mutations are associated with increased risk of breast and ovarian cancers." (PMID 32255263, 2020). "It is known that BRCA1 carriers have a 44% risk of developing ovarian cancer, and there is a 17% risk for BRCA2 carriers." (PMID 32069831, 2020). "As such, germline carriers of BRCA1 and BRCA2 are predisposed to develop breast and ovarian cancers that have a predictable genomic profile." (PMID 32403357, 2020). "In BRCA1 and BRCA2-associated hereditary breast and ovarian cancer, cnLOH was reported as the most common LOH mechanism for second hit inactivation." (PMID 33007869, 2020). "Traditionally, a threshold of greater than 10% lifetime ovarian cancer risk was used, allowing for RRSO in women carrying BRCA1, BRCA2, or mismatch repair gene mutations, which confer lifetime ovarian cancer risk well in excess of 10%." (PMID 33086730, 2020). "Establishing the founder status for several recurrent BRCA2 variants across ethnic groups supports unselected use of the BRCA POC assay in all SA breast/ovarian cancer patients by recent local and international public health recommendations." (PMID 33643918, 2020). "In conclusion, this is the first study in Vietnam to use NGS to investigate mutations of BRCA1 and BRCA2 genes in ovarian cancer patients." (PMID 32856862, 2020). "Somatic reversion mutations and intragenic deletions restoring function of BRCA1 and BRCA2 in patients with known germline BRCA mutations have been well described in chemotherapy-resistant ovarian cancer." (PMID 32403357, 2020). "Background and objective: BRCA1 and BRCA2 are associated with many cancer types in addition to hereditary breast and ovarian cancers." (PMID 32349445, 2020). "Individuals heterozygous mutations of BRCA2 have increased risk of inherited breast and ovarian cancer." (PMID 32168907, 2020). "All four patients who carried germline mutations in both BRCA1 and BRCA2 had a family history of breast/ovarian cancer." (PMID 32455662, 2020). "Germline mutations in the tumor suppressor, BRCA2 (BReast CAncer susceptibility gene 2), have commonly been associated with an increased risk of developing breast and ovarian cancers." (PMID 32638521, 2020). "Secondly, the BRCA1 and BRCA2 mutation ratios in ovarian cancer were relatively low in the SNP data from TCGA." (PMID 33282564, 2020). "Sequencing-based genetic tests to screen for mutations in BRCA1 and BRCA2 are recommended to individuals with a personal or family history of early onset and/or bilateral breast and/or ovarian cancer, or a history of male breast cancer." (PMID 33293522, 2020).
ovarian carcinoma (continued). "Identifying individuals with pathogenic variants in BRCA1 or BRCA2 is critical in the management and prevention of breast and ovarian cancer." (PMID 33081408, 2020). "It is estimated that about 44% of women who inherit a deleterious BRCA1 mutation and about 17% of women who inherit a deleterious BRCA2 mutation will develop ovarian cancer by the age of 80." (PMID 32419845, 2020). "Germline pathogenic variants in the tumour-suppressor genes, BRCA1 and BRCA2, predispose humans to breast and ovarian cancer with reduced effects on the risk of cancer in other tissues." (PMID 33081408, 2020). "Signature 3 is closely associated with germline and somatic BRCA1 and BRCA2 mutations in breast, pancreatic, and ovarian cancers." (PMID 32754579, 2020). "BRCA1 and BRCA2 are the most known genes associated with hereditary breast and/or ovarian cancer (HBOC) risk." (PMID 32380732, 2020). "Germline mutations in BRCA1 confer a cumulative breast and ovarian cancer risk by age 80 of 72% and 44%, respectively, while BRCA2 mutations confer a 69% and 17% increased risk of breast and ovarian cancer by this age, respectively." (PMID 32455662, 2020). "Pathogenic germline variants in the breast cancer susceptibility genes BRCA1 and BRCA2 increase the risk for the development of ovarian cancer (OC) in carriers." (PMID 32850417, 2020). "For example, ovarian cancers harboring inactivating BRCA2 mutations can be specifically treated with poly(ADP-ribose) polymerase (PARP) inhibitors (PARPi)." (PMID 33015624, 2020). "This study was set out to identify BRCA1/BRCA2 mutations in patients at high risk of familial breast and ovarian cancer using a systematic approach." (PMID 33067490, 2020). "Subsequently, in the expansion phase, only ovarian cancer carriers of BRCA1 or BRCA2 mutations were enrolled." (PMID 32481735, 2020). "Germline and somatic variant testing of the BRCA1 and BRCA2 genes are important to predict treatment response to PARP inhibitors in ovarian cancer patients." (PMID 33008098, 2020). "In particular, inactivation of ARID1A in vivo increases tumor-infiltrating lymphocytes and sensitivity to anti-PD-L1 antibody therapy in ovarian cancer, while BRCA2 mutations are enriched in melanomas responsive to ICIs." (PMID 32676589, 2020). "We found 13 patients with the BRCA1 mutation and 13 patients with the BRCA2 mutation out of 274 ovarian cancer patients using the intersection between the mutation data and the immunity cluster data samples." (PMID 33282564, 2020). "One notable example is the PARP inhibitor used in the treatment of inherited breast and ovarian cancer patients with BRCA1 or BRCA2 gene mutations." (PMID 33299637, 2020). "Giving the high prevalence of positive mutations in BRCA1/BRCA2 genes, it is essential to establish a service for familial breast and ovarian cancer service in Jordan and the MENA region, that includes genetic counselling and early genetic screening." (PMID 33067490, 2020). "In conclusion, we have characterized the mutation spectrum of BRCA1/BRCA2 in a consecutive series of ovarian carcinomas, observing a frequency of 19.3% of deleterious variants, 13.3% germline, and 5.9% somatic." (PMID 32850417, 2020). "Olaparib, a polyADP‐ribose polymerase (PARP) inhibitor, is currently used for treatment of ovarian cancer with BRCA2 loss." (PMID 32374087, 2020). "In clear contrast, loss of BRCA1 or BRCA2 is apparently tolerated in breast and ovarian cancers affected by BRCA1 or BRCA2 mutations." (PMID 30626869, 2019). "The contribution of BRCA1 and BRCA2 mutations to the incidence of breast and ovarian cancer has been acknowledged for a number of years." (PMID 30689103, 2019). "Mutations of BRCA1 and BRCA2 are associated with the risk of ovarian cancer at 50% and 20%, respectively." (PMID 30362670, 2019).
ovarian carcinoma (continued). "Hereditary Breast and Ovarian Cancer (HBOC) syndrome is an inherited disorder in which specific genetic mutations (principally BRCA1 and BRCA2 genes) are associated with an increased risk for Breast (BC) and Ovarian Cancer (OC)." (PMID 30841601, 2019). "Mutation analysis of BRCA1 and BRCA2 genes was performed in 44 women diagnosed with primary or recurrent high-grade ovarian cancer from three different samples: blood, cytological sample (ascites, pleural effusion and enlarged lymph nodes) and tumor tissue." (PMID 30940100, 2019). "We identified one case out of 27 (~4%) portraying a deleterious germline mutation in BRCA2, with familial history of breast and ovarian cancer." (PMID 30641862, 2019). "Specific inherited mutations in BRCA1 and BRCA2 increase the risk of female breast and ovarian cancers, and they have been associated with increased risks of several additional types of cancer." (PMID 31865918, 2019). "The aim of the present study is to evaluate the frequency of pathogenic and likely pathogenic variants in BRCA1 and BRCA2 among epithelial ovarian cancer Brazilian patients and compare clinical features of BRCA1/2 carriers and non-carriers." (PMID 30606148, 2019). "Approximately 15% of epithelial ovarian cancers display mutation or loss of BRCA1 or BRCA2, leading to susceptibility to DNA damaging agents." (PMID 31366178, 2019). "Germline mutations in the BRCA1 and BRCA2 genes predispose carriers to breast and ovarian cancer, and there remains a need to identify the specific genomic mechanisms by which cancer evolves in these patients." (PMID 31182087, 2019). "BRCA1 and BRCA2 spliceogenic variants are often associated with an elevated risk of breast and ovarian cancers." (PMID 30736279, 2019). "The estimated penetrance of BRCA1 mutation carriers by age 70 was 65% for BC and 45% for ovarian cancer, and the corresponding rates of BRCA2 mutation carriers were 45% and 11%." (PMID 30940775, 2019). "Current evidence suggests that specific inherited mutations of BRCA1 and BRCA2 are attributed to an enhanced risk of female BC and ovarian cancer (OV)." (PMID 30975222, 2019). "In the West, it was reported that the ovarian cancer risk was higher in the BRCA1 mutation group than in the BRCA2 mutation group, while the prostate cancer risk was higher in the BRCA2 group than in the BRCA1 group." (PMID 31143373, 2019). "DNA microarray analysis in morphologically normal ovarian surface epithelial cells from women with germline mutations of BRCA1 or BRCA2 and ovarian cancer cells identified genes that were up-regulated by DHT treatment." (PMID 30791431, 2019). "Ovarian cancer cells extracted from ascites of platinum‐resistant relapsed ovarian cancers were found to harbour secondary BRCA2 mutations and to be BRCA2‐proficient." (PMID 30672100, 2019). "Platinum-based chemotherapy has been proven to be an effective treatment for BRCA1 and BRCA2 mutated breast and ovarian cancers as these compounds generate DNA cross-links that cannot be easily resolved with an impaired homologous recombination (HR)." (PMID 30871108, 2019). "A high rate of germline BRCA1 and BRCA2 mutations was detected in our retrospective analysis of 392 families with pancreatic cancer associated with breast and/or ovarian cancer." (PMID 30736435, 2019). "Germline mutations in BRCA1 and BRCA2 are associated with greatly increased frequency of breast and ovarian cancers and telomere shortening was associated with genetic anticipation in hereditary breast cancer." (PMID 30995915, 2019). "Women carrying germline pathogenic mutations in BRCA1 and BRCA2 are at high risk of developing breast as well as ovarian cancer." (PMID 31225507, 2019). "The ovarian cancer TCGA confirmed a frequency of 17% germline pathogenic variants in BRCA1 or BRCA2 in 489 unselected ovarian cancer cases." (PMID 30606148, 2019). "The carriers of BRCA1 or BRCA2 gene mutations have very high lifetime risks for breast and ovarian cancers." (PMID 30622657, 2019).
ovarian carcinoma (continued). "Mutations in the BRCA1 and BRCA2 genes predispose carriers to a higher risk of breast and ovarian cancer." (PMID 31671674, 2019). "A recent study found that 3.6% of ovarian cancer patients have germline mutations in BRCA1 while 3.3% have germline mutations in BRCA2." (PMID 30813239, 2019). "Olaparib is the first PARPi approved for the treatment of refractory ovarian cancer harboring BRCA1 or BRCA2 mutations." (PMID 31795418, 2019). "Carriers of BRCA1 and BRCA2 pathogenic variants have a risk of developing ovarian cancer about 45 and 20% until 80 years old, respectively." (PMID 30606148, 2019). "Individuals carrying pathogenic BRCA1 or BRCA2 mutations have an increased lifetime risk of breast and/or ovarian cancer." (PMID 30980249, 2019). "Beyond prostate cancer, germline BRCA1 and BRCA2 mutations are known to increase the risk of other tumor types including breast and ovarian cancers." (PMID 30871108, 2019). "Their germline mutations and, consequently, loss of function were associated with the higher risk of breast (ranging from 57% in BRCA1 mutation to 45% in BRCA2 mutation) and ovarian cancers (ranging from 11% in BRCA1 mutation to 40% in BRCA2 mutation)." (PMID 31109041, 2019). "Compared to the normal population, BRCA1 mutation carriers have an estimated 44% risk of developing ovarian cancer by age 70, while this risk is up to 27% for BRCA2 mutant individuals." (PMID 30813239, 2019). "More recent studies in populations from different countries showed a wider range of frequency of pathogenic variants in BRCA1 or BRCA2 depending on the study, with the highest frequencies found in Asian populations reaching 27% of ovarian cancer patients." (PMID 30606148, 2019). "They reported on the prevalence of BRCA1 and / or BRCA2 mutations among breast or/ and ovarian cancer patients." (PMID 30898109, 2019). "A relative deficiency in TILs was also detected in BRCA2-mutated ovarian cancer when compared to BRCA1-mutated tumors." (PMID 31549213, 2019). "Olaparib is the first PARP1 and PARP2 inhibitor approved for treatment of refractory ovarian cancer harboring BRCA1 or BRCA2 mutation." (PMID 31554189, 2019). "It is well-known that germline mutations in BRCA1 or BRCA2 genes increase risks of breast and ovarian cancer, as well as pancreatic cancer." (PMID 31877165, 2019). "Earlier studies evaluating exclusively ovarian cancer patients found a frequency of 11 to 15% germline pathogenic variants in BRCA1 or BRCA2 among epithelial ovarian cancer patients." (PMID 30606148, 2019). "Germline mutations in BRCA1 and BRCA2 are known risk factors for ovarian cancer, particularly the HGSC subtype." (PMID 31366178, 2019). "BRCA mutations, in either the BRCA1 or BRCA2 gene, are also a well-known category of mutations, as women with harmful mutations in either BRCA1 or BRCA2 are known to have a risk of breast or ovarian cancer that is roughly five to 30 times the normal risk." (PMID 31610621, 2019). "Nowadays CHK2 mutation is studied frequently in hereditary breast and ovarian cancer patients in addition to BRCA1/BRCA2." (PMID 31398194, 2019). "One family was known to carry a pathogenic BRCA2 germline mutation causing hereditary breast and ovarian cancer." (PMID 31212687, 2019). "The variant BRCA2 c.631 + 4A > G was found in a Danish breast and ovarian cancer family and analyzed with a combination of minigene and RT-PCR with the conclusion of a disease causing mutation." (PMID 31143303, 2019). "Signature 3 is strongly associated with germline and somatic BRCA1 and BRCA2 mutations in breast, pancreatic, and ovarian cancers, which was previously reported in GGNs." (PMID 31058088, 2019). "Of particular interest are the high frequency of BRCA2 variants identified in our cohort, which are emerging therapeutic targets in some tumors other than breast and ovarian cancer." (PMID 31133068, 2019).
ovarian carcinoma (continued). "Germline pathogenic variants (PVs) in the BRCA1 and BRCA2 genes confer a significantly increased lifetime risk for the development of both breast and ovarian cancer." (PMID 31336956, 2019). "Female BRCA1 and BRCA2 mutation carriers have an increased lifetime risk of developing breast and/or ovarian cancer." (PMID 31370837, 2019). "Women who carry a BRCA1 or BRCA2 gene mutation are at highest risk of developing ovarian cancer, with a lifetime risk of up to 44% by 80 years of age." (PMID 31061661, 2019). "For BRCA1, the assessed average risk of breast and ovarian cancers ranges from 57 to 65% and 20 to 50%, respectively; for BRCA2, the risk ranges from 35 to 57% and 5 to 23%, respectively." (PMID 31336956, 2019). "EMSY, which is known to be amplified in breast and ovarian cancers, encodes a protein reported to bind and inactivate BRCA2." (PMID 31154673, 2019). "We specifically analyzed SOC, since BRCA2 germline mutations are most frequently found within this subgroup of ovarian cancers." (PMID 30626869, 2019). "Consistent with this, loss of BRCA2 occurs in tumors and is thought to promote tumorigenesis, while BRCA2 heterozygous germline mutations increase susceptibility to breast and ovarian cancer, as well as other cancers." (PMID 31316060, 2019). "BRCA1- and BRCA2-deficient ovarian cancers in an unselected cohort of ovarian cancer patients were also shown to have increased PD-L1 and PD-1 expression compared to BRCA-proficient ovarian cancers." (PMID 31022191, 2019). "Monoallelic germline mutations in the BRCA1 and BRCA2 genes predispose carriers to a high incidence of breast and ovarian cancer." (PMID 31671674, 2019). "Women with BRCA1 and BRCA2 mutations have a higher risk of ovarian cancer at the age of 70 years at 39-46% and 10-27%, respectively." (PMID 30362670, 2019). "BRCA1 and BRCA2 are breast and ovarian cancer susceptibility genes with a strong hereditary component." (PMID 31387612, 2019). "BRCA1 mutation confer a genetic susceptibility to ovarian cancer by almost 60%, however in further studies will be interesting to evaluate the influence of BRCA2 mutation." (PMID 30630446, 2019). "Due to her synchronic breast and ovarian cancers, a genetic profile was performed detecting a new pathogenic variant in the BRCA2 gene: c.3606_3607del (p.Ser1203Cysfs)." (PMID 30723561, 2019). "Cumulative lifetime risk of ovarian cancer associated with a BRCA1 or BRCA2 mutation is estimated at 44% and 17%, respectively, with 15.5% of patients with epithelial ovarian cancer found to carry a mutation." (PMID 29752676, 2018). "Signature 3 (BRCA signature), associated with inactivating BRCA1 or BRCA2 mutations in breast and pancreatic cancers and prevalent in ovarian cancer, is present in 27/39 samples." (PMID 30382883, 2018). "According to the US National Cancer Institute, specific inherited mutations in BRCA1 and BRCA2 increase the risk of female breast and ovarian cancers, “and they have been associated with increased risks of several additional types of cancer." (PMID 29445722, 2018). "Constitutional loss-of-function pathogenic variants in the tumor suppressor genes BRCA1 and BRCA2 are widely known to confer an elevated risk of breast and/or ovarian cancer, and their mutational screening has become a standard in routine diagnostic practice." (PMID 30441849, 2018). "The cumulative estimates of ovarian cancer in Caucasians ranged from 16-68% and 11-27% for BRCA1 and BRCA2 carriers respectively, which are in line with our findings that BRCA2 carriers tend to have a lower risk of ovarian cancer." (PMID 29861850, 2018). "Several successful clinical trials have resulted in PARPi being approved for the treatment of advanced stage BRCA1/BRCA2-deficient ovarian cancer patients that have been pre-treated with chemotherapy, or who have undergone surgery." (PMID 30680069, 2018).